BDNF (brain derived neurotrophic factor)
Diseases named in the same sentence as BDNF in open-access papers (continued):
Sharing a sentence is not in itself a finding about the gene and the disease.
neurodegenerative disease (continued). "We conclude that the slow release of BDNF from chitosan microspheres enhances signaling through NTR and promotes axonal growth in neurons, which could constitute an important therapeutic agent in neurodegenerative diseases and CNS lesions." (PMID 36827132, 2023). "It is not fully defined whether BDNF levels decrease with age in healthy people, however this reduction is well established in elderly patients with neuropsychiatric and neurodegenerative diseases." (PMID 38055476, 2023). "However, these promising miRNAs targeted with BDNF have not been studied with other neurodegenerative diseases." (PMID 32944919, 2021). "The activation of microglia could encourage the production of some protective molecules including brain-derived neurotrophic factor (BDNF) but also proinflammatory cytokines, reactive oxygen and nitrogen species which favor the progression of this neurodegenerative disease." (PMID 30837941, 2019). "Because BDNF itself cannot cross the BBB, further studies focusing on the intracellular BDNF/TrkB transport would be important for the better understanding of the pathophysiology of neurodegenerative diseases and developing new medical treatments in the future." (PMID 30463271, 2018). "Somewhat surprisingly, it now appears that basal levels of BDNF and its receptor TrkB in the brain do not change very much as a result of aging alone, although significant changes are seen in some neurodegenerative diseases." (PMID 29911174, 2018). "Therefore, it is not surprising that changes in BDNF/TrkB signalling pathways are similarly found in neurodegenerative diseases." (PMID 28134845, 2017). "In this model, fingolimod increased the expression of the trophic factor vascular endothelial growth factor α (VEGFα) but not of brain-derived neurotrophic factor (BDNF), which has been shown to increase secondary to fingolimod treatment in other models of neurodegenerative diseases." (PMID 25309325, 2014). "Indeed, BDNF, like LXR, is involved in cholesterol metabolism and in neurodegenerative disease." (PMID 25229406, 2014). "Neurotrophic factors (NTFs), such as nerve growth factor (NGF), brain-derived neurotrophic factor (BDNF) and glial cell-line derived neurotrophic factor (GDNF), play pivotal roles in neuronal development and survival and exhibit therapeutic potential in animal models of neurodegenerative diseases." (PMID 23923031, 2013). "Therefore, it is not surprising that both BDNF and oxidative stress biomarkers have been identified as key markers of brain health and potential targets for expanding preventive and therapeutic strategies to neurodegenerative diseases." (PMID 40361833, 2025). "Moreover, BDNF, CREB, phosphorylated CREB (phospho-CREB), and serotonin have all been shown to be sleep-promoting, and BDNF, phospho-CREB, ACh, and TrkB were all found to be increased after apigenin treatment in a mouse model of amyloid beta (Aβ)-driven neurodegenerative disease." (PMID 38476603, 2024). "Indeed, to date there has been no study to clarify whether the reduction of BDNF levels in neurodegenerative diseases is a downstream consequence of the disease process or part of a specific disease mechanism." (PMID 31627296, 2019). "Further, coactivation of the cholinergic system and the BDNF-CREB pathway in the hippocampus might influence learning and memory processes, which may lead to development of novel therapeutics using acupuncture stimulation at GV20 to treat neurodegenerative diseases." (PMID 25231482, 2014). "Moreover, the connection between peripheral and central BDNF is still currently unknown, and reduced blood BDNF levels have been reported in a multitude of neuropsychiatric and neurodegenerative diseases, as well as in medical diseases, making circulating BDNF a non-specific biomarker." (PMID 32517269, 2020).
tumor (327 papers, 2009 to 2026). "Recently, the regulatory role of BDNF in tumor‐associated axonogenesis and neural infiltration has been elucidated." (PMID 41556039, 2026). "Other biomarker classes, including TNF-receptor signaling, CRP and systemic inflammation indices (NLR, SII, and PIV), IGF-1, CD markers, tumor-associated antigens, and BDNF, were likewise inconsistently related to cognition." (PMID 41228315, 2025). "Through its interaction with a modified form of TrkB, BDNF has been implicated in multiple stages of tumorigenesis, including tumor cell growth, maturation, migration, and invasion." (PMID 41155372, 2025). "Similar IL-1β and TNF-α inputs have been reported to modulate NGF and BDNF levels in bone-associated tumours, suggesting a broader principle whereby inflammatory mediators act as upstream rheostats of neurotrophic output." (PMID 41142827, 2025). "Brain-derived neurotrophic factor is found to be highly expressed in multiple human cancers and associated with tumor growth, invasion, and metastasis." (PMID 38775506, 2024). "In head and neck malignancies, BDNF can be produced by both tumor and stromal cells, including cancer-associated fibroblasts." (PMID 39906323, 2024). "Due to the trophic functions, BDNF is also implicated in tumor development, progression, and survival." (PMID 37298337, 2023). "find that norepinephrine causes tumor cells to secrete brain-derived neurotrophic factor (BDNF) in an β3-ARs/cAMP/EPAC/JNK-dependent manner." (PMID 36707854, 2023). "Elevated expression of BDNF has been in several kinds of human malignancies such as prostate cancer, cervical cancer and brain neoplasms, in association with tumor invasion and unresponsiveness to conventional chemotherapeutic regimens." (PMID 37460933, 2023). "There is also a potential role of one BDNF splicing variant in Marek’s disease (MD) tumour resistance and susceptibility." (PMID 36829208, 2023). "As well, many studies have indicated that BDNF/TrkB signaling was strongly associated with tumor progression." (PMID 36417428, 2022). "After adjusting the correlation for tumor purity, BDNF expression was remarkably associated with immune infiltration level of Th2 cells in PAAD patients (r = 0.214, p = 0.005)." (PMID 34777634, 2021). "In patients with cancer, high tumor nerve counts were significantly associated with increased BDNF and norepinephrine levels and decreased overall survival." (PMID 33339112, 2020). "Brain derived neurotrophic factor (BDNF) was of great interest as it was predicted to be associated with tumorigenic properties (tumor cell proliferation, migration and invasion) as well as inflammatory response." (PMID 30847302, 2019). "With regard to the BDNF/TrkB axis, a high level of TrkB expression has been observed in both cancers and is associated with tumor growth, invasiveness with distant metastases, and poor prognosis." (PMID 30741921, 2019). "We also observed high expressions of both TRKB and BDNF in tumor-associated vessels, even though these vessels appeared to be normal and were located far from the tumor cells in OSCC patients." (PMID 29861866, 2018). "Brain-derived neurotrophic factor and nerve growth factor are both neurotrophins linked to tumor development, promoting proliferation, angiogenesis, and invasion." (PMID 30245591, 2018). "And, in addition, analyze the mechanisms regulating miRNA expression in the brains of tumor-bearing treated and untreated animals, as well as the neuroanatomical and behavioral repercussions of tumor and chemo brain-associated BDNF downregulation." (PMID 29179434, 2017). "Our results suggested that the upregulation of ABCG2 is likely one of the mechanisms that underlies BDNF-induced tumor resistance." (PMID 27852063, 2016).
tumor (continued). "BDNF has multiple alternative splicing variants and plays diverse biological functions in mammals, including neuronal survival, cell differentiation and tumor development." (PMID 26926340, 2016). "Bearing in mind that SFRP1 is a known tumor suppressor gene this association gives insight into a novel putative BDNF function." (PMID 25036590, 2014). "In fact, stable BDNF over-expression in BT20 basal-like cancer cells caused a reduction of tumor cell proliferation." (PMID 25036590, 2014). "BDNF expression was reported to be significantly associated with tumor-progression factors such as poor differentiation, advanced tumor stage, and lymph-node invasion." (PMID 23531103, 2013). "We found that miR-204 acts as a tumor suppressor by targeting the function of genes associated with tumorigenesis, including brain-derived neurotrophic factor (BDNF)." (PMID 23285024, 2012). "Since BDNF/TrkB have been reported to facilitate survival and metastasis of tumor cells, the association between BDNF or TrkB expressions and the presence of intrahepatic dissemination at the time of resection was analyzed statistically in the present study." (PMID 21999199, 2011). "Moreover, BDNF-induced TrkB activation has been implicated in several processes related to tumor progression, including angiogenesis, chemotherapy resistance, invasion, and metastasis." (PMID 41155372, 2025). "This tumour had low BDNF RNA expression, encoding the ligand for TRKB." (PMID 40348911, 2025). "The results showed that BDNF might drive an immunosuppressive tumor microenvironment (TME) by reeducation of tumour-associated macrophages (TAMs) toward a pro-tumorigenic M2 phenotype, particularly in brain metastasis." (PMID 40654575, 2025). "The increased expression of BDNF is closely associated with enhanced tumor invasion and metastasis." (PMID 38775506, 2024). "This raised a preliminary assumption that the association between BDNF and Th2 cells might play an important role in tumor immunity." (PMID 34777634, 2021). "These tumor-associated genes that seemed to be elevated with BDNF expression level increased." (PMID 34777634, 2021). "In contrast, newly arising tumours, due to their high vascularization, might cause relevant changes in serum BDNF levels after a resection." (PMID 34395067, 2021). "BDNF downregulation has been associated with an array of neurological conditions and could be one of the mechanisms underlying tumor brain and chemo brain." (PMID 29179434, 2017). "BDNF/TrkB signaling has been reported to be associated with tumor progression, metastasis, and response to chemotherapy in several human malignancies such as neuroblastoma, ovarian, head and neck, lung, hepatocellular, pancreatic, bladder, prostate, multiple myeloma, and breast tumor." (PMID 24801982, 2014). "By contrast to normal embryonic neural stem cells, such differences in BDNF properties in tumor cells could be a hallmark of tumor invasiveness." (PMID 21966426, 2011). "Neurotrophic factor inhibitors like BDNF and other neurotrophic factors are implicated in tumor growth, inhibiting their signaling pathways (e.g., Trk inhibitors) could be explored for their anti‐tumor effects." (PMID 39469896, 2024). "Importantly, BDNF knockdown profoundly inhibited tumor-associated lymphangiogenesis in vivo." (PMID 28771226, 2017). "Next, we examined whether BDNF knockdown suppresses tumor-associated lymphangiogenesis in vivo." (PMID 28771226, 2017). "Hence, BDNF loss notably increased the risk for early tumor relapse." (PMID 25036590, 2014). "Pharmacologic DGAT1 inhibition suppressed these pathways and elicited racially distinct regulation of tumor-promoting mediators, including BDNF, VEGF, and TSP1." (PMID 42118850, 2026). "Macrophage- and lymphocyte-derived NGF and BDNF establish positive feedforward loops that amplify tumor-neural-immune interactions." (PMID 42212159, 2026).
tumor (continued). "BDNF–TrkB engagement on CD8+ T cells (shown in other tumours) dampens effector cytokines and increases PD-1 via PI3K/AKT-dependent re-programming; OS data are limited." (PMID 41142827, 2025). "The brain-derived neurotrophic factor (BDNF)/tropomyosin-related kinase B (TrkB) axis was shown to facilitate tumor progression and PNI through the EMT in SACC37." (PMID 40084251, 2025). "Nerves secrete neurotrophins such as GDNF, ARTN, and NGF that promote nerve–cancer interactions; BDNF/NTRK signaling implicates in promoting tumor survival." (PMID 40052442, 2025). "BDNF is a critical neurotrophic factor secreted by neurons and tumor cells that significantly influence tumor progression and TME." (PMID 41009819, 2025). "Recombinant TSPAN7 and BDNF IgA antibodies are confirmed to bind tumor cells and recombinant proteins, and control mouse tumor growth." (PMID 40356924, 2025). "NE exposure induced BDNF expression, which acts on TrkB-expressing nerve fibers to drive tumor growth and establish a feedforward neurotrophic loop." (PMID 41009819, 2025). "Targeting the BDNF-TrkB axis offers a promising therapeutic strategy, with preclinical models demonstrating that TrkB inhibitors reduce tumor growth, neural infiltration, and resistance to therapies." (PMID 41009819, 2025). "Immunohistochemistry or multiplex immunofluorescence for NGF, BDNF, TrkA, TrkB, and phospho−Trk can be quantified by digital image analysis across tumor, stromal, and endothelial compartments." (PMID 41383615, 2025). "A clinical study has shown that NSCLC patients with increased BDNF/TrkB expression in tumor tissues have significantly shorter survival than those with low expression." (PMID 40654575, 2025). "Axonal attraction in the OS TME, likely driven by tumour-associated stroma, appears to be mediated by neurotrophic factors such as NGF and BDNF, key regulators of neuronal survival, differentiation, and outgrowth during nerve regeneration." (PMID 41029717, 2025). "BDNF exerts divergent roles in distinct cell types and microenvironments, potentially exhibiting either oncogenic or tumor-suppressive effects." (PMID 41018101, 2025). "BDNF can skew macrophage polarisation toward an immunoregulatory M2 phenotype and modulate cytokine production, changes that are conducive to tumour immune evasion." (PMID 41142827, 2025). "It suggests that iPSC-astrocytes promote tumor cell viability via pathways other than BDNF-related pathways." (PMID 40149331, 2025). "As a key modulator of synaptic plasticity, BDNF contributes to physiological synaptic regulation through neuronal activity and drives tumor progression through BDNF-TrkB-mediated malignant synapse enhancement." (PMID 41018101, 2025). "miR-10a-5p suppresses cancer cell proliferation by directly targeting brain-derived neurotrophic factor (BDNF), thereby inhibiting tumor progression." (PMID 39796267, 2025). "A great part of the research identifying BDNF-target microRNAs concerns investigations on the oncogenicity of BDNF/TrkB signal transduction in tumor cell growth and metastasis." (PMID 38786102, 2024). "In recent years, an increasing number of studies have shown that BDNF is not only related to tumor progression and nervous system development but is also closely associated with the occurrence of neuropathic pain." (PMID 39648800, 2024). "On the other hand, the cAMP/EPAC/JNK signaling pathway promotes BDNF expression in tumor cells, which feedforwards to enhance tumor innervation." (PMID 38233872, 2024). "In colon carcinoma, both BDNF and TrkB are upregulated compared to non-tumor tissues, especially in tumors with advanced clinical stages." (PMID 37610689, 2024). "However, the vector toxicity used in this method can cause protein instability and tumor formation in the local neuron, mainly; protein instability can increase BDNF expression overly and may produce deleterious effects on neuronal circuits, learning, and memory." (PMID 39239097, 2024).
tumor (continued). "The roles of the BDNF/TrkB signaling system in tumor cell proliferation and survival have been deeply demonstrated." (PMID 39469896, 2024). "In vivo studies using nude mice corroborated the tumor-suppressing effects of hsa-miR-134-5p, which were negated by elevated BDNF levels." (PMID 38579169, 2024). "For example, Sustained activation of adrenergic signaling by catecholamines promotes tumor growth and metastasis through enhancing the production of brain-derived neurotrophic factor (BDNF) by tumor cells and BDNF-mediated tumoral innervation." (PMID 38617000, 2024). "Hematoxylin and eosin (H&E) staining revealed that the BDNF-injected TNFR2 KO xenograft tumor tissues had large nuclei and tight spaces, and were present in mitotic cells, characteristics of cancer cells." (PMID 38592583, 2024). "BDNF, secreted by neurons, moves to tumor cells and initiates intracellular signaling cascades that support tumor growth, ultimately helping the tumor to form more and stronger synapses with neurons." (PMID 39469896, 2024). "Research has found that the upregulated activation signals of BDNF/TrkB in tumor cells stimulate a series of downstream pathways, including PI3K/AKT, Ras–Raf–MEK–ERK, PLC‐γ, as well as the transactivation of epidermal growth factor receptor." (PMID 39648800, 2024). "Our in vivo study demonstrated that TNFR2 deficiency decreased tumor growth and SCZ-like behaviors by reducing BDNF and TrkB expression." (PMID 38592583, 2024). "When the cellular mechanisms triggered by BDNF are more strongly activated, tumor cells will respond with stronger currents, which in turn fosters their growth." (PMID 39469896, 2024). "Apart from its role as a neurotrophins, BDNF can also enhance tumor survival, proliferation, and migration by activating the ERK/CREB, PI3K/Akt, and NF‐kB pathways via binding to the TrkB receptor." (PMID 39036344, 2024). "Ongoing research focuses on using these inhibitors to block NGF-TrkA or BDNF-TrkB signaling pathways, thus inhibiting tumor development." (PMID 38081962, 2024). "As growing evidence supports a major role for NF‐kB in oncogenesis, BDNF has also been further investigated in the context of tumor disease." (PMID 36794673, 2023). "Together, these findings indicate that BDNF–TrkB signalling promotes malignant synaptic plasticity and augments tumour progression." (PMID 37914930, 2023). "Meanwhile, tumor cells can produce and release neurotrophic factors like nerve growth factor (NGF) or brain-derived neurotrophic factor to promote tumor innervation." (PMID 37347365, 2023). "Earlier studies suggested an anti-apoptotic and tumor promoting role of BDNF, new evidence points towards promoting anti-tumor immune response and by augmenting sensitivity to chemotherapy." (PMID 38016985, 2023). "It was recently evidenced that BDNF and its receptor TrkB played significant roles in tumor pathology." (PMID 37100464, 2023). "The mean tumor tissue BDNF levels were 8.47 ng/g in patients with GBM IDH-mutant and 23.93 ng/g in patients with GBM IDH-wildtype (p=0.55)." (PMID 38050515, 2023). "Due to the significantly lower CSF and plasma BDNF levels in the study group, compared to controls, we expected that tumor size and peritumoral edema would be related to CSF and plasma BDNF levels." (PMID 38050515, 2023). "Elevated plasma levels of BDNF have been found in several types of cancer and play an important role in tumor proliferation, survival, migration, and invasion." (PMID 36825022, 2023). "Even at early stages, it has been reported that the release of neurotrophic factors including nerve growth factor, glial cell line-derived neurotrophic factor and brain-derived neurotrophic factor is an essential component of tumor progression." (PMID 37027061, 2023). "Within tumor tissue, the average BDNF level was 14.23 ng/g tissue, with a range spanning from 1.75 to 54.55 ng/g and a median value of 6.01 ng/g." (PMID 38050515, 2023).